RET (ret proto-oncogene)
Diseases named in the same sentence as RET in open-access papers (continued):
Sharing a sentence is not in itself a finding about the gene and the disease.
papillary thyroid carcinoma (continued). "We compared the ERK score, a measure of ERK activity derived from RNAseq data, from RET-rearranged, BRAF mutant, and RAS mutant papillary thyroid cancers in TCGA patients, and we found that RET-rearranged cancers have significantly higher ERK scores than either BRAF or NRAS/HRAS mutant tumors." (PMID 35510953, 2022). "Based on the finding of a RET rearrangement, we treated the patient with cabozantinib (XL184), a nonselective RET inhibitor known to have antitumor activity in differentiated thyroid cancer." (PMID 35510953, 2022). "A broad range of anti-tumor activity of pralsetinib on multiple advanced RET fusion-positive solid tumors in addition to NSCLC has also been reported; tumor type includes papillary thyroid cancers, undifferentiated thyroid cancer, pancreatic cancer, colon cancer, etc.." (PMID 33109256, 2020). "RET fusion kinase occurs in nearly one-third of papillary thyroid cancer and ∼ 2% of lung adenocarcinoma, but is not yet identified in CRC." (PMID 26078337, 2015). "In particular, we analyzed transgenic mice carrying TRK and RET/PTC3 oncogenes, which develop papillary thyroid carcinomas (PTC) and N-ras mice that develop thyroid follicular tumors that undergo dedifferentiation, predominantly follicular thyroid carcinoma (FTC)." (PMID 26030152, 2015). "Also previous reports have demonstrated the LIM protein Enigma as a required component for mitogenic signaling of RET/PTC, a rearranged oncogenic isoform of RET found in papillary thyroid carcinomas." (PMID 24466333, 2014). "Presently, the best known form of such alterations in papillary thyroid cancer is the concept of oncogenic RET/PTC1 and RET/PTC3 sequences that are also present in chronic lymphocytic thyroiditis, but with no clinical manifestation of lesions in the thyroid parenchyma." (PMID 23099542, 2013). "A number of gene alterations, such as point mutations in RAS and BRAF genes, point mutations or amplification of PIK3CA, and fusion genes involving RET, NTRK1 and PPARγ are known to frequently occur in differentiated thyroid carcinoma, and are correlated to different morphological subtypes." (PMID 22087789, 2011). "Therefore, breakage at RET and CCDC6 can lead to the formation of RET/PTC1 translocations in sporadic tumors through a fragile site-mediated mechanism, resulting in the development of sporadic papillary thyroid carcinomas." (PMID 21286310, 2010). "Rearrangements of the RET oncogene were found in 44% of papillary carcinomas in which we studied fresh material; none of the tumours examined showed mutation in any of the other genes." (PMID 10646883, 2000). "CCDC6 was first identified in papillary thyroid carcinoma as a result of the rearrangement of an unknown amino-terminal sequence with the tyrosine kinase domain of the RET proto-oncogene." (PMID 39684377, 2024). "Interestingly, PTCs have been found to overexpress wild type tyrosine kinase RET mRNA with over expression in 70% of papillary thyroid cancers relative to expression in non-neoplastic thyroid tissue." (PMID 38566816, 2024). "RET fusions which occur due to chromosomal rearrangements resulting in RET protein’s C-terminus splicing with the N-terminus of another protein and are seen in papillary thyroid carcinomas, NSCLC in young never-smokers, advanced disease, and poorly differentiated populations." (PMID 36582799, 2022). "Recent research has further suggested that papillary carcinomas harbour a different genetic background according to the association or not with thyroiditis (expression of BRAFV600E in cases without and expression of RET/PTC in cases with autoimmunity)." (PMID 28572821, 2017). "Interestingly, an increasing prevalence of RET/PTC1 over RET/PTC3 rearrangements has been observed in sporadic papillary thyroid carcinomas, which is consistent with the experimental data and further supports fragile site involvement in sporadic papillary thyroid carcinomas." (PMID 21286310, 2010).
papillary thyroid carcinoma (continued). "Two major isoforms of RET, RET9, and RET51, are expressed in papillary thyroid carcinoma (PTC), but information on the level of RET expression is lacking." (PMID 38532419, 2024). "The common RET fusions found are KIF5B-RET, CCDC6-RET, NCOA4-RET and TRIM33-RET and they are not restricted to NSCLC, but can also be found in papillary thyroid carcinoma and myelonocytic leukemia." (PMID 29455659, 2018). "Conversely, UbcH10 protein was absent in normal mouse thyroid tissue and in the papillary carcinomas originating from TRK and RET/PTC3 mice." (PMID 16106252, 2005). "In addition, we examined the RET fusion positive to the RET fusion negative papillary thyroid carcinoma (PTC) cohorts and found that the age of the RET fusion positive PTC cohort was significantly younger then the RET fusion negative PTC cohort (33 vs 62 years old <0.001)." (PMID 36690680, 2023).
multiple endocrine neoplasia type 2 (205 papers, 2002 to 2026). Multiple endocrine neoplasia type 2 (MEN2) is a multiple endocrine neoplasia, a polyglandular cancer syndrome characterized by the occurrence of medullary thyroid carcinoma (MTC), pheochromocytoma (PCC), in one variant, primary hyperparathyroidism (PHPT). "Germline gain-of-function point mutations in RET are associated with multiple endocrine neoplasia type 2 (MEN2), while somatic mutations are found in sporadic MTCs, predominantly seen in adults." (PMID 40361475, 2025). "Germline mutations in human RET are responsible for the autosomal dominant genetic syndromes multiple endocrine neoplasia type 2 (MEN2) and familial MTC." (PMID 41353477, 2025). "Multiple Endocrine Neoplasia Type 2 (MEN2) is an autosomal dominant disease caused by pathogenic variants in the receptor tyrosine kinase RET, with strong genotype-phenotype correlations." (PMID 40316714, 2025). "Multiple endocrine neoplasia type 2 (MEN2) is a rare autosomal dominant disorder caused by germline mutations in the RET proto-oncogene." (PMID 41487748, 2025). "Postoperative multigene panel testing identified a mutation in RET c.1901G > T (p.Cys634Phe) leading to the diagnosis of multiple endocrine neoplasia type 2A." (PMID 39559597, 2024). "Summary of RET mutations and associated clinical features in Multiple Endocrine Neoplasia Type 2 (MEN2)." (PMID 39439561, 2024). "In the germline, point mutations of RET are responsible for multiple endocrine neoplasia type 2 and familial medullary thyroid carcinoma." (PMID 38734621, 2024). "Multiple endocrine neoplasia type 2 occurs due to recurrent heterozygous activating mutations in the proto-oncogene RET." (PMID 39398337, 2024). "The NF1, RET, and VHL genes, which were identified in the 1990s, are associated with neurofibromatosis type 1 (NF1), multiple endocrine neoplasia type 2 (MEN2A), and von Hipple-Lindau (VHL) disease, respectively." (PMID 39559597, 2024). "Pheochromocytoma and paraganglioma are often associated with hereditary syndromes, particularly those involving genes such as RET, which is linked to multiple endocrine neoplasia type 2A." (PMID 39559597, 2024). "Pathogenic variants in the RET proto-oncogene cause multiple endocrine neoplasia type 2 (MEN2) and familial medullary thyroid cancer (FMTC); penetrance and clinical presentation varies according to the type and location of the variants." (PMID 38700789, 2024). "Le Groupe d’Etude des Tumeurs a Calcitonine Prevalence and parental origin of de novo RET mutations in multiple endocrine neoplasia type 2A and familial medullary thyroid carcinoma." (PMID 38806713, 2024). "The connection with RET pathogenic variants is less understood amid the confirmation of multiple endocrine neoplasia type 2, thus the importance of addressing this topic from a practical multidisciplinary approach." (PMID 39585007, 2024). "Germline activating RET mutations are associated with multiple endocrine neoplasia type 2 (MEN2) syndromes, while somatic RET mutations are found in ~ 65% of all sporadic MTCs." (PMID 37435488, 2023). "Multiple endocrine neoplasia type 2 (MEN2) is a multi-system disease associated with GPVs of the RET gene and has an autosomal dominant inheritance pattern." (PMID 37258796, 2023). "One patient was molecularly confirmed to have multiple endocrine neoplasia type 2 due to a pathogenic variant in the RET gene, which allowed for cascade screening in her sibling who also carried the variant." (PMID 36820377, 2023). "Mutation of the RET oncogene is associated with familial medullary thyroid carcinoma (including in multiple endocrine neoplasia type 2A and 2B)." (PMID 35328664, 2022). "One familial multiple endocrine neoplasia type 2 (MEN2) sample (Patient_15) revealed an expected germline RET mutation." (PMID 34069252, 2021). "RET germline mutations are associated with multiple endocrine neoplasia type 2A (MEN2A), MEN2B and familial medullary thyroid carcinoma." (PMID 34094913, 2021).
multiple endocrine neoplasia type 2 (continued). "RET R982C and Y791F mutations were reported in patients with multiple endocrine neoplasia type 2, but unreported in meningiomas up to now." (PMID 33670055, 2021). "Prophylactic TT is recommended in patients with MTC who have an RET germline mutation and the resulting multiple endocrine neoplasia type 2A (MEN2A) or multiple endocrine neoplasia type 2A (MEN2B) syndrome." (PMID 34640473, 2021). "Hirschprung's disease co-occurs with multiple endocrine neoplasia type 2A infrequently but at a higher rate with certain RET mutations." (PMID 34987852, 2021). "Germline RET mutations and variants are involved in development of multiple endocrine neoplasia type 2 (MEN2)." (PMID 33827484, 2021). "Activating variants in the receptor tyrosine kinase REarranged during Transfection (RET) cause multiple endocrine neoplasia type 2 (MEN 2), an autosomal dominantly inherited cancer-susceptibility syndrome." (PMID 34925234, 2021). "The mutations of the cysteine-rich domain in RET is frequently shown in multiple endocrine neoplasia type 2A (MEN2A) or familial medullary thyroid carcinoma (FMTC)." (PMID 32571297, 2020). "Oncogenic gain-of-function RET mutations were originally found in multiple endocrine neoplasia type 2 (MEN2)." (PMID 35582449, 2020). "Multiple endocrine neoplasia type 2A (MEN 2A) is a rare syndrome caused by RET germline mutations and has been associated with primary hyperparathyroidism (PHPT) in up to 30% of cases." (PMID 32375120, 2020). "Multiple endocrine neoplasia type 2 (MEN 2) is an autosomal dominant inherited cancer syndrome caused by germline mutations of the rearranged during transfection (RET) proto-oncogene." (PMID 32375120, 2020). "Due to the founder effect of the C611Y mutation in Denmark, a large proportion of the Danish multiple endocrine neoplasia type 2A (MEN2A) cohort comprise patients with RET mutations classified in the American Thyroid Association moderate risk level." (PMID 30618340, 2019). "In about 75% of cases it is sporadic while, in case of RET mutation, it is associated to multiple endocrine neoplasia type 2 (25% of cases)." (PMID 31619220, 2019). "Loss-of-function mutations in RET are responsible for Hirschsprung disease, while gain-of-function mutations for multiple endocrine neoplasia type 2." (PMID 35582269, 2019). "Genetic testing revealed a pathogenic heterozygous RET mutation associated with multiple endocrine neoplasia type 2 (MEN2)." (PMID 31263477, 2019). "PASS and GAPP were applied on 41 PCCs; 13 PCCs were diagnosed in ten multiple endocrine neoplasia type 2A (MEN 2A) patients carrying established germline RET proto-oncogene mutations, as well as 28 assumed sporadic PCCs." (PMID 29779047, 2018). "RET missense mutations are known to be causally associated with MEN2 syndrome (multiple endocrine neoplasia type 2)." (PMID 30446652, 2018). "Activating mutations of the RET gene are associated with the development of three distinct clinical syndromes: multiple endocrine neoplasia types 2 and 3 (traditionally named MEN2A/MEN2B) and familial medullary thyroid cancer (FMTC)." (PMID 28965289, 2017). "Germline mutations in the RET gene that enhance its activity are associated with Sipple syndrome (multiple endocrine neoplasia type 2, MEN2) comprising two subtypes, MEN2A and MEN2B." (PMID 28187001, 2017). "The RET gene is known to be involved in neurocristopathies such as Hirschsprung disease and Multiple Endocrine Neoplasia type 2, in the presence of loss-of-function and gain-of-function mutations, respectively." (PMID 27034161, 2016). "Two de novo germline RET mutations previously associated with late-onset multiple endocrine neoplasia type 2 were identified in patients OS-224 and OS-242." (PMID 26632267, 2015). "We report a rare case with pheochromocytoma as the first manifestation of multiple endocrine neoplasia type 2A with RET mutation S891A." (PMID 24449023, 2014).
multiple endocrine neoplasia type 2 (continued). "Multiple endocrine neoplasia type 2 is an autosomal dominant syndrome caused by germline activating mutations of the RET proto-oncogene which encodes for RET, a receptor tyrosine kinase that modulates C cell proliferation and apoptosis." (PMID 25086465, 2014). "Although they are a minor subset, RET mutations in MEN2A cases are also identified within the intracellular domain, including those originally reported as mutations of familial medullary thyroid carcinoma (FMTC)." (PMID 24449023, 2014). "In Multiple Endocrine Neoplasia type 2B investigations include acetylcholinesterase study of rectal mucosa followed by the molecular analysis of RET mutation." (PMID 23651601, 2013). "Known mutations in RET lead to gain of function and to autophosphorylation of tyrosine sites within RET and have been directly implicated in the molecular pathophysiology of multiple endocrine neoplasia type 2 (MEN-2)." (PMID 23455356, 2013). "The genetic study revealed a heterozygous mutation, c.1900T>C, in the RET proto-oncogene that confirmed the diagnosis of multiple endocrine neoplasia type 2A (MEN2A)." (PMID 23514614, 2013). "Multiple endocrine neoplasia type 2 (MEN2) is a rare familial syndrome caused by mutations in the RET protooncogene and it is transmitted as an autosomal dominant trait." (PMID 23093970, 2012). "Loss-of-function mutations in RET cause Hirschsprung's disease, a developmental disorder of the enteric nervous system, whereas gain-of-function mutations cause multiple endocrine neoplasia type 2a or b (MEN2a/b), a dominantly inherited cancer syndrome." (PMID 22355350, 2012). "In one study there is a suggestion about duplication of the mutant RET allele in trisomy 10 or loss of the wild-type allele in multiple endocrine neoplasia type 2-associated pheochromocytomas." (PMID 23093970, 2012). "Multiple endocrine neoplasia type 2 (MEN2) is a rare familial syndrome caused by mutations in the RET protooncogene." (PMID 23093970, 2012). "Germline mutations of RET are found in multiple endocrine neoplasia type 2 (MEN 2) and Hirschsprung disease (HSCR) in an autosomal dominant pattern." (PMID 21655256, 2011). "A small molecule inhibitor, arylidene-2-indolinone (RPI-1), abolishes the constitutive tyrosine phosphorylation caused by the specific RET proto-oncogene mutation seen at cysteine residue 634 in the syndrome multiple endocrine neoplasia type 2A (MEN2A)." (PMID 20862373, 2010). "Multiple endocrine neoplasia type 2 (MEN 2) is a rare hereditary cancer syndrome caused by germline variants in the REarranged during Transfection (RET) proto-oncogene and is subdivided into MEN 2A and MEN 2B, with a point prevalence of 13–24 per million and 0.9–1.65 per million, respectively." (PMID 37046785, 2023). "Although the large majority of cases are sporadic, up to 25% of MTC disclose a genetic predisposition, due to a germline RET gene mutation, which also drives other endocrinological tumours in the framework of the syndrome Multiple Endocrine Neoplasia type 2 (MEN2)." (PMID 36910603, 2023). "Biopsy of eyelid and tongue lesions confirmed that these were mucosal neuromas, and subsequent genetic testing confirmed the diagnosis of multiple endocrine neoplasia type 2B (MEN2B) identifying de novo point mutations in the RET proto‐oncogene (M918T, G691S, S904S)." (PMID 37013117, 2023). "Thus, we retrospectively investigated synergistic effect of C634Y and V292M RET germline mutations in family members with multiple endocrine neoplasia type 2A." (PMID 32989896, 2020). "Germline mutations in RET are linked with multiple endocrine neoplasia type 2 (MEN2)." (PMID 30925729, 2019).